INPP4B (inositol polyphosphate-4-phosphatase type II B)
Description:
Catalyzes the hydrolysis of the 4-position phosphate of phosphatidylinositol 3,4-bisphosphate, inositol 1,3,4-trisphosphate and inositol 3,4-trisphosphate. Plays a role in the late stages of macropinocytosis by dephosphorylating phosphatidylinositol 3,4-bisphosphate in membrane ruffles. The lipid phosphatase activity is critical for tumor suppressor function. Antagonizes the PI3K-AKT/PKB signaling pathway by dephosphorylating phosphoinositides and thereby modulating cell cycle progression and cell survival.
Tractability: PROTAC: ubiquitination databases record sites on it.
Gene: Protein-coding gene on chromosome 4 (142,023,160 to 142,847,432, reverse strand). Ensembl gene ENSG00000109452.
Subcellular location (Human Protein Atlas): Centrosome
Pathways (Reactome):
Metabolism: Synthesis of IP2, IP, and Ins in the cytosol; Synthesis of PIPs at the early endosome membrane; Synthesis of PIPs at the plasma membrane
Gene Ontology:
Molecular function: inositol-1,3,4-trisphosphate 4-phosphatase activity; phosphatidylinositol-3,4-bisphosphate 4-phosphatase activity; protein binding; inositol-3,4-bisphosphate 4-phosphatase activity; phosphatase activity
Biological process: inositol phosphate metabolic process; phosphatidylinositol biosynthetic process; signal transduction; phosphatidylinositol-3-phosphate biosynthetic process
Cellular component: cytoplasm; cytosol
Genetic constraint (gnomAD): Loss-of-function variants: 29 observed, 61.85 expected, observed/expected ratio (o/e) 0.47, 90% interval 0.35 to 0.64. The upper end of that interval is the gene's LOEUF score, 0.64, which puts it in group 2 of 6, group 1 being the genes least tolerant of losing a copy. Missense variants: 680 observed, 733.76 expected, observed/expected ratio (o/e) 0.93, 90% interval 0.87 to 0.99. Synonymous variants: 277 observed, 270.75 expected, observed/expected ratio (o/e) 1.02, 90% interval 0.93 to 1.13.
Homologues: Orthologues: chimpanzee INPP4B (96% identical), macaque INPP4B (94% identical), mouse Inpp4b (91% identical), rabbit INPP4B (90% identical), pig INPP4B (90% identical), guinea pig INPP4B (89% identical), rat Inpp4b (87% identical), dog INPP4B (86% identical), tropical clawed frog inpp4b (67% identical), zebrafish inpp4b (51% identical), Drosophila melanogaster CG42271 (28% identical), Caenorhabditis elegans inpp-4B (20% identical). Paralogues in human: INPP4A (42% identical).
Diseases named in the same sentence as INPP4B in open-access papers:
INPP4B is named in the same sentence as 84 diseases in open-access papers, as found by Europe PMC text mining. Sharing a sentence is not in itself a finding about the gene and the disease. The quoted sentences say what the papers report.
breast carcinoma (56 papers, 2011 to 2025). "Genetic alterations in INPP4B, including mutations and changes in expression levels, have been identified in breast cancer." (PMID 38172946, 2024). "As a predictive biomarker, the status of INPP4B is associated with clinical outcomes in breast cancer patients." (PMID 38172946, 2024). "Using the METABRIC and TCGA datasets, we found that only 1% of breast cancers exhibited INPP4B genetic alterations such as mutations, truncations, amplifications, or deletions." (PMID 34035258, 2021). "Increased INPP4B mRNA and protein expression was detected in 14–40% of breast cancers associated with ER-positivity and mutant PIK3CA expression." (PMID 34035258, 2021). "Decreased INPP4B expression was associated with triple-negative breast cancers, and notably increased INPP4B expression was demonstrated in 25% of breast cancers associated with ER/PR-positivity and the luminal subtype (, e)." (PMID 34035258, 2021). "Further stratification revealed high INPP4B expression was specifically associated with the PIK3CA-mutant ER+ breast cancer subset." (PMID 34035258, 2021). "In basal-like breast cancer patients, reduced INPP4B expression is associated with poor survival rate." (PMID 32296634, 2020). "Conversely, emerging findings in malignancies including acute myeloid leukemia (AML), colon cancer, melanoma and breast cancer among others suggest that overexpression of INPP4B is also associated with promoting aggressive cancer phenotypes." (PMID 31695845, 2019). "For instance in melanoma and breast cancer, both INPP4B loss and INPP4B overexpression were associated with downstream oncogenic signaling through Akt and SGK3, respectively." (PMID 31695845, 2019). "Clinically, loss of INPP4B expression in breast cancer was associated with decreased patient survival." (PMID 29415082, 2018). "INPP4B mRNA expression is lost in a cohort of basal-like breast cancers and its reduced expression is associated with higher tumour grade and worse survival." (PMID 28082369, 2017). "INPP4B is the target of frequent copy number loss in a variety of solid tumors including the majority of basal-like breast cancers, ovarian cancers and melanomas." (PMID 25868852, 2015). "In basal-like breast cancer, DNA copy number loss of INPP4B was found to be associated with genomic instability and poor patient outcome." (PMID 25868852, 2015). "Loss of function of the phosphatases PTEN and inositol polyphosphate 4-phosphatase type II (INPP4B) is associated with aggressive basal-like breast carcinoma." (PMID 24460909, 2014). "Loss of INPP4B protein in breast cancer occurs most frequently in aggressive hormone receptor-negative basal-like breast carcinomas, with higher tumor grade, size, and increased proliferation." (PMID 21487159, 2011). "However, an increase in INPP4B protein expression was observed in 14–40% of breast cancers relative to normal tissue associated with ER/PR-positivity and the luminal (ER+ and/or PR+) breast cancer subtype (, c)." (PMID 34035258, 2021). "INPP4B expression was also significantly higher in breast cancers with multiple PIK3CA mutations." (PMID 34035258, 2021). "Indeed, negativity for INPP4B has been identified as a marker for basal-like breast cancer with protein loss in 84% of basal-like breast cancers and loss-of-heterozygosity in 55% of triple-negative, basal-like cancers." (PMID 32085745, 2020). "INPP4B protein loss was also frequently observed in PTEN-null tumors showing the existence of co-occurent loss of two phosphoinositide phosphatases in human breast cancer." (PMID 27374081, 2016). "In the same study, INPP4B protein expression was frequently lost in primary human breast carcinoma cells, associated with high clinical grade and large tumors and loss of expression of hormone receptors, and lost most often in aggressive basal-like breast carcinomas." (PMID 22121480, 2012).
breast carcinoma (continued). "Finally loss-of-function mutations in type II phosphatidylinositol 4’ phosphatase (INPP4B) also occur in breast cancer." (PMID 21646685, 2011). "However, in mammary tumors INPP4B loss is observed more frequently in patients who have also lost PTEN." (PMID 21487159, 2011). "So, the ER+ breast cancer cells with INPP4B overexpression were more sensitive to Pyrvinium, which is ascribed to the inhibitory effect of Pyrvinium on the WNT/β-catenin pathway." (PMID 39253139, 2024). "The comprehensive research on INPP4B as a predictive biomarker also encompasses understanding its role within the broader molecular landscape of breast cancer." (PMID 38172946, 2024). "In breast cancer, INPP4B has emerged as a potential predictive biomarker, offering valuable insights into disease prognosis and treatment response." (PMID 38172946, 2024). "In almost half of all ER+ breast cancers, the oncogene phosphoinositide phosphatase INPP4B is highly expressed and can promote WNT/β-catenin activation." (PMID 39253139, 2024). "In PIK3CA-mutant ER+ breast cancer cells, INPP4B localizes prominently to late endosomes via its interaction with the small GTPase Rab7." (PMID 37471270, 2023). "The porcupine O-acyltransferase (PORCN) inhibitors LGK-974 or IWP-2, which prevent Wnt ligand secretion, rescued the increased proliferation of INPP4B-overexpressing ER+ breast cancer cells." (PMID 37471270, 2023). "In PIK3CA-mutant ER+ breast cancer, PI3Kα signaling promotes INPP4B-dependent lysosomal degradation of GSK3β, which enhances Wnt/β-catenin activation." (PMID 37471270, 2023). "Fittingly, INPP4B overexpression in cervical cancer and ductal carcinoma cells decreased tumor growth in mice, and INPP4B knockdown in breast cancer cells increased the number and size of tumors in an athymic murine xenograft model." (PMID 36993823, 2023). "The phosphoinositide phosphatase, INPP4B, is overexpressed in almost half of all ER+ breast cancers, and promotes Wnt/β-catenin signaling, cell proliferation and tumor growth." (PMID 36612130, 2022). "Altogether, these data indicate that INPP4B has minimal effect on the sensitivity of PIK3CA-mutant ER+ breast cancer cells in monolayer culture to estrogen or PI3Kα-targeted therapies." (PMID 36612130, 2022). "Pyrvinium or 4-OHT-pyrvinium treatment also rescued the increased size of INPP4B-overexpressing ER+ breast cancer 3D spheroids." (PMID 36612130, 2022). "INPP4B overexpression promotes PIK3CA-mutant ER+ breast cancer cell proliferation and tumor growth via activation of Wnt/β-catenin signaling, suggesting that INPP4B functions as an oncogene in this context." (PMID 36612130, 2022). "We reported that INPP4B expression is increased in up to 46% of ER+ breast cancer relative to normal breast tissue, correlating with mutant PIK3CA expression." (PMID 36612130, 2022). "Here, we identify the FDA-approved Wnt inhibitor pyrvinium as a potential adjunct treatment for ER+ breast cancers with increased INPP4B expression." (PMID 36612130, 2022). "INPP4B overexpression had little effect on the sensitivity of ER+ breast cancer cells to the SERM afimoxifene/4-hydroxytamoxifen (4-OHT) or the PI3Kα inhibitor alpelisib when cells were grown in monolayer cultures." (PMID 36612130, 2022). "Examination of four small molecule Wnt inhibitors revealed that ER+ breast cancer cells with INPP4B overexpression were more sensitive to the FDA-approved drug pyrvinium and a 4-OHT-pyrvinium combination treatment." (PMID 36612130, 2022). "Here, we demonstrate that breast cancer cells with increased expression of the oncogene INPP4B, a PI3K regulator that promotes Wnt/β-catenin activation, are selectively sensitive to pyrvinium treatment in 2D and 3D culture." (PMID 36612130, 2022).
breast carcinoma (continued). "INPP4B is a bona fide marker of ER-positivity and exhibits increased expression in up to 46% of ER+ breast cancers where it promotes Wnt-mediated cell proliferation and tumor growth." (PMID 36612130, 2022). "Together, these data identify pyrvinium as a promising Wnt inhibitor for targeting ER+ breast cancers with high INPP4B expression, that is effective at low nanomolar concentrations in combination with 4-OHT." (PMID 36612130, 2022). "INPP4B expression is increased in almost half of all ER+ breast cancers, which promotes cell proliferation and tumor growth via activation of Wnt/β-catenin signaling." (PMID 36612130, 2022). "As INPP4B promotes ER+ breast cancer cell proliferation and tumor growth via enhanced Wnt/β-catenin signaling, we predict that pyrvinium reduces cell viability via Wnt/β-catenin suppression." (PMID 36612130, 2022). "This suggests that INPP4B plays a dual role as an oncogene and tumor suppressor in breast cancer via activation of alternate PI3K-dependent signaling pathways." (PMID 34035258, 2021). "Our discovery that INPP4B promotes oncogenic signaling in PIK3CA-mutant ER+ breast cancer, despite suppressing AKT signaling, suggests Wnt/β-catenin rather than AKT activation is responsible for the hyper-proliferation." (PMID 34035258, 2021). "To investigate this apparent paradox, we utilized an integrative approach featuring proteomics, transcriptomics, and advanced cellular imaging to elucidate the molecular mechanisms by which INPP4B promotes tumorigenesis of PIK3CA-mutant ER+ breast cancers." (PMID 34035258, 2021). "Here, we further explored the role INPP4B plays in ER+ breast cancer revealing a cohort of PIK3CA-mutant ER+ breast cancers exhibit increased INPP4B expression." (PMID 34035258, 2021). "We utilized several unbiased proteomics-based techniques to characterize the downstream signaling functions of INPP4B in PIK3CA-mutant ER+ breast cancer." (PMID 34035258, 2021). "Knockdown of INPP4B enhances the proliferation and migration of breast cancer, melanoma and prostate cancer cell lines, which, suggests its TSG role in these cancer cells." (PMID 33879096, 2021). "As a phosphoinositide phosphatase, INPP4B has been reported to be expressed at low levels, and to plays a tumour suppressive role in human prostate cancer, breast cancer and ovarian cancer by negatively regulating PI3K-Akt signaling." (PMID 33879096, 2021). "Our independent analysis of primary ER+PIK3CA-mutant breast cancers, which exhibit high INPP4B expression, identified these and additional upregulated Wnt genes (LEF1, MYCN, FZD7, SFRP2, TCF7L1, CTNNB1, FZD4, and SFRP1)." (PMID 34035258, 2021). "Here we demonstrated endogenous and ectopically-expressed INPP4B localized to late endosomes of ER+ breast cancer cells." (PMID 34035258, 2021). "Several studies have proven that INPP4B expression was inhibited in digestive cancers, acute myeloid leukemia, melanomas, and breast cancer due to the deletion of the INPP4B chromosome region, and served as an oncogenic factor." (PMID 35070988, 2021). "Increased mRNA expression of AXIN2 (1.9-fold), LEF1 (2.3-fold), and DKK1 (3.2-fold) was also observed in T47D cells expressing GFP-INPP4B, demonstrating that INPP4B enhances Wnt/β-catenin signaling in PIK3CA-mutant ER+ breast cancer cells." (PMID 34035258, 2021). "Using representative breast cancer cell lines, we also demonstrated elevated expression of miR-17 and miR-19a in BL1, coincident with suppressed expression of CDKN1A, FAM214A, and INPP4B, validating the patient-derived association." (PMID 32085745, 2020). "Compelling evidence has delineated the carcinogenesis of INPP4B in breast cancer, laryngeal cancer and melanoma." (PMID 30876449, 2019). "In particular, LOH at the INPP4B locus frequently occurred in basal-like (triple negative) breast cancers, characterized by poor clinical outcome." (PMID 29415082, 2018).
breast carcinoma (continued). "In human breast cancer models, INPP4B suppressed epithelial cell transformation, proliferation and anchorage-independent growth in an AKT-dependent manner." (PMID 29415082, 2018). "For instance, INPP4B can promote the growth and proliferation of ER+ breast cancer cells through SGK-3, a family member of serine/threonine kinases closely related to AKT." (PMID 29415082, 2018). "Firstly, we detected INPP4B in several cervical cancer cell lines with breast cancer MCF‐7 cells used as a positive control." (PMID 29516642, 2018). "In line with those of the previous studies in prostate cancer, basal‐like breast cancer and ovary cancer, our results reveal the suppressive role of INPP4B in tumorigenesis of cervical cancer." (PMID 29516642, 2018). "INPP4B shRNA knockdown in breast cancer cell lines increased cell proliferation, motility, anchorage-independent cell growth, xenograft tumour growth and disrupted mammary acini morphology in an AKT-dependent manner." (PMID 28082369, 2017). "In breast cancer cells, increased SGK3 phosphorylation was associated with increased INPP4B expression, as well as PIK3CA and PTEN mutations." (PMID 28082369, 2017). "INPP4B has important implications in breast cancer that include DNA repair defects, increased genomic instability, and inhibition of the PI3K pathway." (PMID 27923045, 2016). "Nevertheless, INPP4B-dependent activation of SGK3 drives tumourigenesis in a subset of breast cancers with low Akt." (PMID 26573229, 2015). "In contrast, introduction of INPP4B into MDA-MB-231 breast cancer cells that similarly had low levels of endogenous INPP4B caused decreases in cell proliferation and Akt activation." (PMID 26573229, 2015). "Decreased INPP4B expression has been reported to contribute to prostate and breast cancer development." (PMID 25277204, 2014). "Especially, INPP4B suppressor function is in contrast with ERα tumor promoting roles in breast cancer." (PMID 25277204, 2014). "Genetic and genomic alterations in the PI3K pathway were previously found in all breast cancer subtypes, with basal-like cancers having more loss of pathway inhibitors PTEN and INPP4B, and with luminal A cancers having more mutations in PIK3CA." (PMID 24386073, 2013). "Conversely, reexpression of INPP4B in ER-negative, INPP4B−/− human breast cancer cells reduced Akt activation and anchorage-independent growth." (PMID 22121480, 2012). "In particular, INPP4B protein expression is lost in 84% of human basal-like breast carcinomas, which are generally highly aggressive with poor clinical outcomes and frequently associated with BRCA1 gene mutations." (PMID 22121480, 2012). "The INPP4B locus is located on chromosome 4q31.21, a region that is frequently deleted in breast cancer cell lines and high-grade basal-like breast tumors as determined using high-resolution comparative genomic hybridization analysis." (PMID 22121480, 2012). "In human mammary epithelial cells and breast cancer cell lines, INPP4B was able to suppress both basal and insulin-like growth factor-induced Akt phosphorylation." (PMID 22121480, 2012). "Somewhat differently from HMECs and breast cancer cells, INPP4B inhibits phosphorylation of Akt and its downstream target FOXO3a in prostate cancer cells with or without PTEN expression." (PMID 21487159, 2011). "Preclinical investigations have suggested that breast cancer cells exhibiting reduced INPP4B expression may display heightened sensitivity to selective inhibitors of the PI3K pathway, presenting a promising avenue for targeted therapeutic strategies." (PMID 38172946, 2024). "This may be influenced by the genetic or epigenetic profile of these distinct breast cancer subsets, such as the presence of PIK3CA mutations and increased INPP4B, or the expression of effectors that mediate PI3K suppression of Wnt signaling." (PMID 37471270, 2023).